SIX1 (SIX homeobox 1)
Diseases named in the same sentence as SIX1 in open-access papers (continued):
Sharing a sentence is not in itself a finding about the gene and the disease.
branchio-oto-renal syndrome (11 papers, 2009 to 2026). "SIX1 variants underlying Branchio-oto-renal syndrome occur in the SIX domain (SD) or homeodomain (HD)." (PMID 42290293, 2026). "SIX1 mutation causes human branchio-oto-renal syndrome (BOR), characterized by hearing loss, auricular deformities, residual branchial arches, and renal abnormalities." (PMID 36845386, 2023). "Six1 is a key transcriptional regulator of many developmental processes and several single nucleotide mutations are causative for Branchio-oto-renal syndrome (BOR) and Deafness, autosomal dominant 23 (DFNA23)." (PMID 37854072, 2023). "Six1 plays an important role in embryonic development and is one of the pathogenic genes of human Branchio-oto-renal syndrome (BOR)." (PMID 36845386, 2023). "Both genes are expressed in nephron progenitors of human fetal kidneys, and mutations in SIX1 or SIX2 cause branchio-oto-renal syndrome or renal hypodysplasia respectively." (PMID 35178390, 2022). "In humans, mutations in SIX1 are associated with Branchio-oto-renal syndrome (BOR), which is characterized by ear, kidney and branchial arch anomalies." (PMID 34739029, 2021). "In particular, mutations in developmental genes are associated with human deafness: for example Six1 or Eya1 mutations are known to cause Branchio-Oto-Renal Syndrome, an autosomal dominant disorder." (PMID 28264836, 2017). "Some of these are included in complex clinical syndromes such as branchio-oto-renal syndrome (EYA1, SIX1), renal-coloboma syndrome (PAX2), renal cysts and diabetes syndrome (TCF2/HNF1B) and Townes–Brocks syndrome (SALL1)." (PMID 28647851, 2018).
glaucoma (11 papers, 2012 to 2023). Increased pressure in the eyeball due to obstruction of the outflow of aqueous humor. "We observed that rs10483727—the only SIX1/SIX6 SNP previously associated with glaucoma susceptibility by GWAS—was in close linkage disequilibrium (LD) with rs33912345 (R-sq = 0.99 in the JPT 1000 genomes dataset)." (PMID 28663559, 2017). "Of these, only the CDKN2BAS and SIX1/SIX6 regions were significantly associated with glaucoma in the meta-analysis, although several other previously identified gene regions demonstrated suggestive associations including SALL1, LRP1B and SIRPA." (PMID 22570617, 2012). "Gene variation of SIX homeobox 1 (SIX1) is also related to a higher risk for glaucoma." (PMID 36769067, 2023). "SIX1/SIX6 polymorphism has been shown to be associated with glaucoma." (PMID 32719476, 2020). "Because VFD in this region typically results from early-stage glaucoma, SIX1/SIX6 could be associated with initial changes in GON; however, optic fissure closures—known as colobomas—also present in this area." (PMID 28663559, 2017). "Homeobox genes such as SIX6/SIX1, LMX1b and MEIS, which play prominent roles in development, have been shown to be associated with glaucoma." (PMID 36148008, 2022). "The significance of the SIX1/SIX6 locus in glaucoma has been previously discovered for VCDR and POAG, whereas the subsequent research confirmed a direct correlation between polymorphisms in this region and glaucoma onset." (PMID 32545285, 2020). "Furthermore, the fine-sectored cpRNFLT analysis indicated that SIX1/SIX6 polymorphisms would affect cpRNFL thinning at 281.3–303.8°, which corresponds to parafoveal scotoma in a visual field test of glaucoma patients." (PMID 28663559, 2017). "A meta-analysis using data from six independent studies comprising 3,161 glaucoma cases and 42,837 controls found evidence for rs190004 (near ATOH7), rs1063192 (in CDKN2B and the overlapping gene CDKN2B-AS1) and rs10483727 (near SIX1 gene) significantly associated with POAG." (PMID 22761751, 2012). "Despite the known association between SIX1/SIX6 SNPs and glaucoma development, these patients were not specifically excluded from the study population since we did not perform visual field testing or slit lamp biomicroscopy required for this diagnosis." (PMID 28663559, 2017).
lung carcinoma (11 papers, 2015 to 2024). "TFAP2A- and SIX1- specific staining was clearly observed in the nucleus of the lung cancer cells including HIV associated squamous cell carcinoma (SCC) and AC." (PMID 30177858, 2018). "Promoter methylation of SIX1 was shown to impact its expression, and high expression of SIX1 was reported to activate the Notch signaling pathway and predict poor prognosis in lung cancer patients." (PMID 38970307, 2024). "In 24 of the 26 unique analyses, SIX1 expression was elevated in cancer tissues than in normal tissues, including 6 analyses related to lung cancer." (PMID 35069900, 2022). "Consistently, TCGA-LUAD and TCGA-LUSC samples in the UALCAN database also showed elevated mRNA level of SIX1 in lung cancer tissues." (PMID 35069900, 2022). "In contrast, various adult pathologies demonstrate inappropriately increased SIX1 expression in adult tissues, including breast, esophageal, and lung cancers." (PMID 35420997, 2022). "Among the many predicted targets, seven genes (SOX4, ZEB2, AVL9, PTPN9, RAB22A, ITGB8 and SIX1) that have been reported to play an oncogenic role in lung cancer were further analyzed." (PMID 35287543, 2022). "Six homeobox 1 (SIX1) and Notch receptor 2 (NOTCH2) protein expressions have been associated with invasive lung cancer, by inducing EMT and thus promoting advanced malignant phenotypes." (PMID 35444536, 2022). "All these results indicate that the expression levels of SIX1 and TFAP2A are specifically increased in HIV-associated lung cancer." (PMID 30177858, 2018). "The expression levels of SIX1 and TFAP2A are specifically increased in HIV-associated lung cancer and are associated with poorly differentiated tumor tissue." (PMID 30177858, 2018). "In in vitro study, they demonstrated that silencing of endogenous SIX1 attenuated proliferation and invasion of lung cancer, which supported our clinical analysis." (PMID 27821176, 2016). "We found that SIX1, PROM1, and TFAP2A were upregulated in HIV-associated lung cancer." (PMID 30177858, 2018). "Also, previous study indicated that SIX1 participated in TGF-β1-induced EMT in lung cancer tissues." (PMID 32065213, 2020). "For instance, previous report demonstrated that SIX1 expression was markedly increased in NSCLC and miR-204/SIX1 pathway might be a therapeutic approach for the treatment of lung cancer." (PMID 32065213, 2020).
prostate carcinoma (11 papers, 2012 to 2024). A carcinoma that arises from epithelial cells of the prostate gland. "This study suggests that Six1 could be served as an additional biomarker in identifying prostate cancer patients at risk of tumor progression, might potentially be used for predicting survival outcome of patients with prostate cancer." (PMID 26161040, 2015). "For Six1 IHC staining in prostate cancer tissues and normal prostate tissues, immunoreactivity was seen primarily in the cytoplasm and perinucleus of prostate cancer cells." (PMID 26161040, 2015). "Increased expression of Six1 protein was observed in the majority of prostate cancer, compared with their paired adjacent normal prostate tissues." (PMID 26161040, 2015). "Further studies are needed to clarify the precise mechanism of Six1 in prostate cancer and to develop potential therapies targeting Six1 in prostate cancer." (PMID 26161040, 2015). "Meanwhile, the high expression rate of Six1 protein was significantly higher in high pN grade (N1 + N2) prostate cancers (81.1 %, 73/90) than in low pN grade cases (N0) (13.0 %, 7/54) (P < 0.001)." (PMID 26161040, 2015). "Western blotting revealed that up-regulation expression of Six1 was detected in prostate cancer, when compared with adjacent normal prostate tissues." (PMID 26161040, 2015). "In this study, the protein and/or mRNA expression of Six1 was first examined by Western blotting and/or qRT-PCR in 8 pairs of primary prostate cancer and adjacent normal prostate tissues." (PMID 26161040, 2015). "It’s been widely demonstrated that SIX1 was over-expressed in prostate cancer." (PMID 36750914, 2023). "However, the Six1 expression status and its relationship with the clinicopathological characteristics in prostate cancer were unclear." (PMID 26161040, 2015). "When Six1 high expression percentage was determined to be above 55 % (area under ROC curve = 0.881, P = 0.000), high expression of Six1 was observed in 55.6 % (80/144) of prostate cancer tissues and low expression of Six1 was observed in all normal prostate tissues by IHC." (PMID 26161040, 2015). "The high expression of Six1 was detected in 80 ⁄ 144 (55.6 %) of prostate cancer cases." (PMID 26161040, 2015). "In summary, the study suggests that increased expression of Six1 may represent a more aggressive status of prostate cancer." (PMID 26161040, 2015). "Thus, the present study first analyzed the SIX1 expression pattern in liver, colon, breast, ovarian, kidney, lung, thyroid, and prostate cancers using cDNA arrays; the array represented tissues from 3 non-malignant samples and 9 tumor samples of 8 different cancer types." (PMID 37427884, 2023). "The upregulation of SIX1 was related to poor prognosis in many malignancies, such as cervical cancer, CRC, prostate cancer, and so on." (PMID 36750914, 2023). "A significantly increase in both protein and mRNA expression of Six1 was detected in prostate cancer tissues compared to adjacent nontumorous tissues." (PMID 26161040, 2015). "However, Six1 protein expression was not related with patient age, distant metastasis in prostate cancer (P > 0.05)." (PMID 26161040, 2015).
hearing loss (10 papers, 2009 to 2024). "All eight affected individuals with SIX1 variants displayed non-syndromic hearing loss (DFNA23) or atypical BO syndrome." (PMID 37479820, 2023). "Individuals carrying a heterozygous SIX1 mutation were reported to have a very different clinical outcomes, ranging from being non-syndromic bilateral hearing loss to Branchio-otic (BO) syndrome and to Branchio-otic-renal (BOR) syndrome." (PMID 36482904, 2022). "In terms of the clinical features of all BO/BOR-affected patients with EYA1 and SIX1 gene variants (19 probands and their family members who carried the same variants; 34 patients in total), the most frequent symptom was hearing loss (31/ 32, 97%)." (PMID 31427586, 2019). "SIX1 is associated with branchiootorenal syndrome, which is characterized by branchial arch anomalies, hearing impairment (malformations of the auricle with pre-auricular pits and conductive or SN hearing impairment), and renal malformations." (PMID 34440452, 2021). "Consequently, additional reports on SIX1 variants may help delineate the range of SIX1-related phenotypes and define the phenotypic characterization associated with non-syndromic hearing loss (DFNA23) or atypical BO syndrome." (PMID 37479820, 2023). "Mutations in human SIX1 and SIX2 have been associated with multiple congenital disorders such as branchio-oto-renal syndrome (BOR), renal dysplasia, hearing loss, and frontonasal dysplasia syndrome." (PMID 34490256, 2021). "Independent of BOR, dominantly inherited hearing loss has been associated with mutations in both SIX1 and SIX2." (PMID 34490256, 2021). "Analysis of the additional 23 genes indicated a heterozygous SIX1 mutation, c.328C >T (p.R110W), in the subjects with hearing loss but not in subject I:1 with normal hearing." (PMID 24164807, 2013). "There was a lower incidence of major and minor criteria, except hearing loss, among individuals with SIX1 variants compared to clinical EYA1 variant cohorts, and the phenotypic features related to DFNA23 or atypical BO syndrome were highlighted in SIX1 variants." (PMID 37479820, 2023). "Consequently, our results have significant clinical implications, suggesting SIX1 as a potential candidate gene for individuals with non-syndromic hearing loss (DFNA23) and/or preauricular fistula, even without the typical BOR/BO syndrome features." (PMID 37479820, 2023).
melanoma (10 papers, 2019 to 2022). A malignant, usually aggressive tumor composed of atypical, neoplastic melanocytes. "Thus, underlying the mechanisms of SIX1 regulation in melanoma and the upstream factors of SIX1 would be conducive to clinical treatments." (PMID 32258386, 2020). "miR-489-3p acts as an anti-oncogenic miRNA by attenuating the expression of distal-less homeobox 1, which shows pro-tumor effects; miR-489-3p can inhibit the proliferation, migration, and migration of melanoma cells by inhibiting SIX1." (PMID 35184643, 2022). "Similar effect on extracellular acidification in melanoma has miR-150-5p, which similarly to miR-489-3p, inhibits SIX1, and thus reduces aerobic glycolysis." (PMID 33918883, 2021). "In melanoma patients’ samples, miR-489-3p level negatively correlated with SIX1 production, while its overexpression led to decreased proliferation, migration, invasion, and lactate production in vitro and reduced tumor volume in vivo." (PMID 33918883, 2021). "In accordance with miR-489-3p inhibition of SIX1 in cultured cells, expression of SIX1 was inversely correlated with miR-489-3p expression in melanoma." (PMID 32258386, 2020). "We proved that miR-489-3p not only inhibits the Warburg effect in melanoma, but also suppresses melanoma growth and metastasis through inhibition of the SIX1-mediated Warburg effect." (PMID 32258386, 2020). "Here, we show that miR-489-3p suppresses SIX1 expression by directly targeting its 3′ untranslated region (3′ UTR) in melanoma cells." (PMID 32258386, 2020). "Our study confirmed the importance of the miR-489-3p/SIX1 axis in the Warburg effect and melanoma tumorigenesis and progression." (PMID 32258386, 2020). "The specificity of the SIX1 antibody was testified by IHC of melanoma tissues or immunoblotted with cell lysates." (PMID 32258386, 2020). "Taken together, these data collectively suggest that miR-489-3p dampens glycolysis via inhibition of SIX1 expression in melanoma cells." (PMID 32258386, 2020). "miR-489-3p inhibits melanoma cell proliferation, invasion, and metastasis by directly targeting SIX1 expression by binding to its 3′ UTR." (PMID 32258386, 2020). "Possible mechanisms explaining its favorable activity in melanoma are the inhibition of the transcription factor MYB and its association to aerobic glycolysis through SIX1 repression." (PMID 33003444, 2020). "Taken together, these results suggest that the miR-489-3p/SIX1 axis is critical for melanoma cell proliferation, migration, and invasion." (PMID 32258386, 2020). "Taken together, these results suggest that miR-489-3p inhibits SIX1 expression by targeting its 3′ UTR in melanoma cells." (PMID 32258386, 2020). "To investigate the role of SIX1 in melanoma, we used two target prediction programs, TargetScan and miRanda, to screen for miRNAs that target SIX1." (PMID 32258386, 2020). "Collectively, our study demonstrates the importance of the miR-489-3p/SIX1 axis in melanoma, which can be a potential and a promising therapeutic target in melanoma." (PMID 32258386, 2020). "Overexpression of miR-489-3p mimics inhibited SIX1 expression in the melanoma cell lines A375 and SK-MEL-2." (PMID 32258386, 2020). "Clinically, miR-489-3p is downregulated in melanoma patients and negatively correlated with SIX1, which is upregulated in melanoma patients." (PMID 32258386, 2020). "Our data link the miR-489-3p/SIX1 axis to melanoma growth and progression, suggesting potential therapeutic strategies for melanoma." (PMID 32258386, 2020). "On the one hand, miR-150 has been described to suppress proliferation, migration and invasion of melanoma cells through inhibition of SIX1 and downregulation of MYB." (PMID 33228711, 2020). "miR-489-3p suppressed melanoma cell proliferation, migration, and invasion through inhibition of SIX1." (PMID 32258386, 2020).
melanoma (continued). "Mechanistically, the miR-489-3p/SIX1 axis regulates melanoma cell growth and metastasis by controlling glycolysis and mitochondrial respiration both in vitro and in vivo." (PMID 32258386, 2020). "The methylation status of VEGFC, ANGPT2, and SIX homeobox 1 (SIX1) promoters was also found to correlate with overall survival in melanoma patients." (PMID 31069961, 2019). "Enhanced reduced representation bisulfite sequencing‐based methylome profiling revealed for the first time a link between abnormal VEGFC, ANGPT2, and SIX1 gene expression and promoter hypomethylation in melanoma cells." (PMID 31069961, 2019). "In addition, miR-489-3p inhibits proliferation, migration, and invasion in melanoma cells via silencing SIX1." (PMID 35413838, 2022). "Coincidentally, PITX2 and SIX1 could regulate the glycolytic rate of mouse muscle and human melanoma, respectively." (PMID 33567786, 2021). "However, the role of SIX1 in melanoma and the upstream regulating mechanisms of SIX1 remain to be further investigated." (PMID 32258386, 2020). "Importantly, glycolysis regulated by the miR-489-3p/SIX1 axis is critical for its regulation of melanoma growth and metastasis both in vitro and in vivo." (PMID 32258386, 2020). "In melanoma patients, miR-489-3p abundance is negatively correlated with SIX1 expression." (PMID 32258386, 2020). "To confirm whether miR-489-3p might influence glycolysis via SIX1 in melanoma cells, we performed measurement of glucose uptake, lactate production, and ATP generation." (PMID 32258386, 2020). "miR-489-3p was proved as a novel SIX1-targeting miRNA in melanoma cells." (PMID 32258386, 2020). "In melanoma patients, miR-489-3p expression is negatively correlated with SIX1 expression." (PMID 32258386, 2020). "In summary, we showed a novel mechanism that miR-489-3p regulates the transcription factor SIX1-mediated glycolysis in melanoma both in vitro and in vivo, The ability to target SIX1 by miR-489-3p elevates current understanding of the regulatory network of SIX1." (PMID 32258386, 2020). "By directly targeting SIX1, miR-489-3p inhibits melanoma cell glycolysis, growth, and progression." (PMID 32258386, 2020). "We tested if the miR-489-3p/SIX1 axis played similar functions in melanoma cells." (PMID 32258386, 2020). "Taken together, these data suggest the miR-489-3p/SIX1 axis may be a promising way to treat melanoma patients." (PMID 32258386, 2020). "Moreover, the upstream regulating mechanisms and the distinct functions that mediate SIX1 in melanoma remain to be further investigated." (PMID 32258386, 2020). "Meanwhile, we examined the effect of the miR-489/SIX1 axis on melanoma metastasis." (PMID 32258386, 2020). "Moreover, SIX1 knockdown inhibited the ability of miR-489-3p to regulate these functions of melanoma cells." (PMID 32258386, 2020). "As we observed an epigenetic regulation of Vegfc, Angpt2, and Six1 in our mouse melanoma model, we analyzed whether the promoter methylation of these genes could predict overall survival in melanoma patients by a Cox multivariate analysis." (PMID 31069961, 2019). "The miR-489-3p/SIX1 axis may be a promising therapeutic target for melanoma." (PMID 32258386, 2020). "However, the in vivo metastatic functions and the clinical significance of SIX1 in melanoma are unknown." (PMID 32258386, 2020). "Moreover, we identified VEGFR‐3 and ANGPT2 expression, as well as VEGFC, ANGPT2, and SIX1 promoter methylation, as independent prognostic factors for overall survival in melanoma patients, showing the high translational relevance of our findings obtained in a murine model." (PMID 31069961, 2019). "We assessed SIX1 expression by immunohistochemical staining (IHC) and miR-489-3p expression by miRNA in situ hybridization (MISH) in 39 human melanoma samples." (PMID 32258386, 2020). "However, the role of SIX1 in melanoma remains largely unknown." (PMID 32258386, 2020).